SLC25A4 (solute carrier family 25 member 4)
Description:
ADP:ATP antiporter that mediates import of ADP into the mitochondrial matrix for ATP synthesis, and export of ATP out to fuel the cell. Cycles between the cytoplasmic-open state (c-state) and the matrix-open state (m-state): operates by the alternating access mechanism with a single substrate-binding site intermittently exposed to either the cytosolic (c-state) or matrix (m-state) side of the inner mitochondrial membrane (By similarity). Substrate exchange across the membrane occurs consecutively with one substrate being transported first, then dissociating from the substrate binding site before the second substrate binds for transport in the opposite direction. In addition to its ADP:ATP antiporter activity, also involved in mitochondrial uncoupling and mitochondrial permeability transition pore (mPTP) activity. Plays a role in mitochondrial uncoupling by acting as a proton transporter: proton transport uncouples the proton flows via the electron transport chain and ATP synthase to reduce the efficiency of ATP production and cause mitochondrial thermogenesis (By similarity). Proton transporter activity is inhibited by ADP:ATP antiporter activity, suggesting that SLC25A4/ANT1 acts as a master regulator of mitochondrial energy output by maintaining a delicate balance between ATP production (ADP:ATP antiporter activity) and thermogenesis (proton transporter activity) (By similarity). Proton transporter activity requires free fatty acids as cofactor, but does not transport it (By similarity). Also plays a key role in mPTP opening, a non-specific pore that enables free passage of the mitochondrial membranes to solutes of up to 1.5 kDa, and which contributes to cell death. It is however unclear if SLC25A4/ANT1 constitutes a pore-forming component of mPTP or regulates it (By similarity). Acts as a regulator of mitophagy independently of ADP:ATP antiporter activity: promotes mitophagy via interaction with TIMM44, leading to inhibit the presequence translocase TIMM23, thereby promoting stabilization of PINK1 (By similarity).
Synonyms: ANT 1; AAC1; ANT1; T1; ANT; MTDPS12; MTDPS12A; PEO2; PEO3; PEOA2
Tractability: Antibody: its Gene Ontology location is reachable by antibodies, with high confidence; UniProt predicts a signal peptide or a membrane-spanning region. PROTAC: ubiquitination databases record sites on it; its protein half-life has been measured.
Target class: Electrochemical transporter; Transporter; SLC25 family of mitochondrial transporters; SLC superfamily of solute carriers
Gene: Protein-coding gene on chromosome 4 (185,143,233 to 185,150,382, forward strand). Ensembl gene ENSG00000151729.
Subcellular location: Mitochondrion inner membrane; Membrane
Subcellular location (Human Protein Atlas): Mitochondria
Pathways (Reactome):
Disease: Vpr-mediated induction of apoptosis by mitochondrial outer membrane permeabilization
Metabolism: Mitochondrial Uncoupling
Protein localization: Mitochondrial protein import
Transport of small molecules: Transport of nucleosides and free purine and pyrimidine bases across the plasma membrane
Gene Ontology:
Molecular function: ATP:ADP antiporter activity; protein binding; adenine transmembrane transporter activity; oxidative phosphorylation uncoupler activity; proton transmembrane transporter activity
Biological process: ADP transport; mitochondrial ADP transmembrane transport; mitochondrial ATP transmembrane transport; negative regulation of necroptotic process; adaptive thermogenesis; generation of precursor metabolites and energy; positive regulation of mitophagy; regulation of mitochondrial membrane permeability; adenine transport; proton transmembrane transport; transmembrane transport
Cellular component: membrane; mitochondrial inner membrane; mitochondrion; mitochondrial membrane; mitochondrial permeability transition pore complex; plasma membrane
Genetic constraint (gnomAD): Loss-of-function variants: 9 observed, 22.85 expected, observed/expected ratio (o/e) 0.39, 90% interval 0.24 to 0.69. The synonymous counts are far from expectation, so gnomAD's model fits this gene poorly and the ratio says little. Missense variants: 242 observed, 360.01 expected, observed/expected ratio (o/e) 0.67, 90% interval 0.6 to 0.75. Synonymous variants: 103 observed, 136.66 expected, observed/expected ratio (o/e) 0.75, 90% interval 0.64 to 0.89.
Gene-disease validity (ClinGen):
ClinGen rates the evidence that SLC25A4 causes each of these diseases.
mitochondrial DNA depletion syndrome 12B (cardiomyopathic type), autosomal recessive (autosomal recessive): Definitive.
Leigh syndrome (autosomal dominant): Limited. A progressive neurological disease defined by specific neuropathological features associating brainstem and basal ganglia lesions.
Homologues: Orthologues: chimpanzee SLC25A4 (100% identical), dog SLC25A4 (97% identical), pig SLC25A4 (96% identical), rat Slc25a4 (96% identical), guinea pig SLC25A4 (95% identical), mouse Slc25a4 (95% identical), macaque SLC25A4 (91% identical), zebrafish slc25a4 (89% identical), tropical clawed frog slc25a4 (85% identical). Paralogues in human: SLC25A5 (89% identical), SLC25A6 (88% identical), SLC25A31 (72% identical), SLC25A12 (31% identical), SLC25A13 (30% identical), SLC25A43 (28% identical), SLC25A32 (27% identical), SLC25A29 (27% identical), SLC25A16 (27% identical), SLC25A14 (26% identical), SLC25A24 (26% identical), SLC25A42 (26% identical), and 37 more.
Diseases named in the same sentence as SLC25A4 in open-access papers:
SLC25A4 is named in the same sentence as 82 diseases in open-access papers, as found by Europe PMC text mining. Sharing a sentence is not in itself a finding about the gene and the disease. The quoted sentences say what the papers report.
cardiomyopathy (13 papers, 2016 to 2025). A disease of the heart muscle or myocardium proper. "A frame-shift null mutation (c.523delC, p.Q175RfsX38) of SLC25A4 resulted in autosomal recessive myopathy and cardiomyopathy." (PMID 35237671, 2021). "Mutations in SLC25A4 are associated with different mitochondrial disorders including phenotypes of mitochondrial myopathy, exercise intolerance, cardiomyopathy, and progressive external ophtalmoplegia." (PMID 29404805, 2018). "A homozygous SLC25A4 (c.368C>A, p.Ala123Asp) mutation was previously identified in a patient with mitochondrial myopathy and cardiomyopathy." (PMID 30165862, 2018). "Moreover, a homozygous mutation in SLC25A4 has been found to cause myopathy and cardiomyopathy with multiple mtDNA deletions in skeletal muscle tissue." (PMID 41165044, 2025). "Additionally, the loss of function of the SLC25A4 gene can lead to severe cardiomyopathy, scoliosis, cataracts, and depression." (PMID 39135208, 2024). "However, mutations in SLC25A4 have been associated with mt-dysfunction-induced muscle weakness and cardiomyopathy." (PMID 35563877, 2022). "FBXL4, ANT1, AGK, and SLC25A4 have been confirmed to be associated with cardiomyopathy." (PMID 35237671, 2021). "It is more commonly associated with autosomal-recessive deficiency of SLC25A4 (cardiomyopathy types of the disease [MIM: 617184 and 615418]), another mtDNA maintenance gene, although variable mtDNA deletions are usually associated with dominant pathogenic variants in this gene." (PMID 28942965, 2017). "Several heterozygous SLC25A4 mutations cause adult-onset autosomal-dominant progressive external ophthalmoplegia associated with multiple mitochondrial DNA deletions, whereas recessive SLC25A4 mutations cause childhood-onset mitochondrial myopathy and cardiomyopathy." (PMID 27693233, 2016). "In mice, SLC25A4 knockouts result in mitochondrial myopathy and cardiomyopathy, and severe intolerance to exercise." (PMID 35073835, 2022). "SLC25A4 knockout (SLC25A4−/−) mice develop cardiomyopathy and myopathy as well." (PMID 40556660, 2025). "It is worth mentioning that a single gene may have a different status in several panels, i.e. SLC25A4 is rated as ‘green’ in the ‘Cardiomyopathies – including childhood onset’ panel and as red in the ‘Hypertrophic cardiomyopathy – teen and adult’ panel." (PMID 36825469, 2023).
hypertrophic cardiomyopathy (5 papers, 2013 to 2023). A condition in which the myocardium is hypertrophied without an obvious cause. "Specifically SLC25A4 is connected with progressive external ophthalmoplegia and familial hypertrophic cardiomyopathy, TLR-3 with susceptibility or resistance to some kinds of infections, F11 with deficiency in coagulation factor XI and CYP4V2 with Bietti crystalline corneoretinal dystrophy." (PMID 24176130, 2013). "Interesting, SLC25A4 knockout mice exhibit phenotypes of hypertrophic cardiomyopathy, exercise intolerance, and lacticacidemia." (PMID 34946914, 2021).
autosomal dominant progressive external ophthalmoplegia (3 papers, 2016 to 2020). Autosomal dominant form of progressive external ophthalmoplegia. "In particular, in Drosophila sesB1, the point mutation L289F was found to be adjacent to the site of the V298M mutation in the human SLC25A4, which was detected in patients with autosomal dominant progressive external ophthalmoplegia (adPEO)." (PMID 32842667, 2020).
kidney cancer (3 papers, 2020 to 2021). Primary or metastatic malignant neoplasm involving the kidney. "In kidney cancer, SLC22A6, SLC22A7, SLC22A13, SLC25A4, SLC34A1, and SLC44A4 were significantly downregulated." (PMID 32461965, 2020).
progressive external ophthalmoplegia (3 papers, 2013 to 2020). A mitochondrial myopathy characterized by slowly progressive paralysis of the levator palpebrae, orbicularis oculi, and extraocular muscles. "One observation that has been held in favour is the autosomal dominant inheritance of progressive external ophthalmoplegia, which is caused by missense mutations in the gene coding for the human ADP/ATP carrier 1, also called SLC25A4 or ANT1." (PMID 32725219, 2020).
acute myocardial infarction (2 papers, 2024 to 2025). Necrosis of the myocardium, as a result of interruption of the blood supply to the area. "The expression of SLC25A4 was found increased in hearts of the myocardial infarction and SLC25A4 was identified as a biomarker of the apoptosis-associated cardiomyocyte subcluster with single-cell data of from Gene Expression Omnibus database." (PMID 40556660, 2025). "Twice the normal levels of Mb were recently associated with early acute myocardial infarction; Slc25a4 is included in the DIA pathway and Cox6a2 is included in the CMC, OXP, and DIA pathways." (PMID 38534766, 2024).
bipolar disorder (2 papers, 2016 to 2018). A disorder of the brain that causes unusual shifts in mood, energy, activity levels and the ability to carry out day-to-day tasks. "In a family of bipolar disorder and autosomal dominantly inherited chronic external ophthalmoplegia (CPEO), the L98P mutation of ANT1 (adenine nucleotide translocator 1, SLC25A4) was identified." (PMID 29892051, 2018). "The mitochondrial-related proteins (ATP5H, SSBP1, SLC25A4 and NDUFV2) previously shown to be differentially expressed in the PSD in schizophrenia were also differentially expressed in the PSD in bipolar disorder." (PMID 27898073, 2016).
cardiac hypertrophy (2 papers, 2009 to 2021). "SLC25A4 is active in cardiac hypertrophy and myopathy after mutation." (PMID 33589646, 2021). "Network analysis mapping protein–protein interactions and synergistic actions of AR using multi-component networks reveal drug targets such as ACADM, COX4I1, COX6B1, HBB, MYH14, and SLC25A4, as potential pharmacological co-targets for cardiac hypertrophy." (PMID 33589646, 2021).
colon cancer (2 papers, 2022). "The results showed that SLC25A4 and SLC25A23 were, respectively, decreased in gastric cancer and colon cancer, while SLC25A7 was increased in gastric cancer, which was consistent with our bioinformatics prediction." (PMID 36254139, 2022). "At the mRNA level of specimens, we found that SLC25A4 and SLC25A23 were, respectively, decreased in gastric cancer and colon cancer, while SLC25A7 was increased in gastric cancer, which was consistent with our bioinformatics prediction." (PMID 36254139, 2022). "SLC25A4 was downregulated in gastric cancer specimens, while SLC25A23 was downregulated in colon cancer specimens without statistical significance." (PMID 36254139, 2022).
gastric cancer (2 papers, 2022). A primary or metastatic malignant neoplasm involving the stomach. "To verify the positive results in result 3.8, we further detected the expression of SLC25A7 in gastric and intestinal cancer, SLC25A4 in gastric cancer, and SLC25A23 in intestinal cancer by immunohistochemistry." (PMID 36254139, 2022). "SLC25A4, which is downregulated in gastric cancer and upregulated in acute monocytic leukemia (AML), was found to be a biomarker in renal cell carcinoma." (PMID 35288533, 2022).
myocardial ischemia (2 papers, 2022 to 2026). A disorder of cardiac function caused by insufficient blood flow to the muscle tissue of the heart. "SLC25A4 is an effective protective factor in myocardial ischemia with an important role in keeping mitochondrial integrity and decreasing oxidative stress in infarcted heart tissue when it is overexpressed." (PMID 35563680, 2022). "ISOV exerts cardioprotective effects against myocardial ischemia by directly binding to SLC25A4 and activating the AMPK/PGC-1α pathway, highlighting its potential as a therapeutic agent for myocardial ischemia." (PMID 42196177, 2026).
prion disease (2 papers, 2024 to 2025). A transmissible disease that is caused by a protein that is able to induce abnormal folding of normal cellular proteins, leading to characteristic spongiform brain changes, which are associated with neuronal loss without an inflammatory response. "We compare down/up-regulated proteins from C− versus 5RINM with altered proteins related to chemical carcinogenesis, reactive oxygen species (e.g., down-regulated P48962/Slc25a4, P51881/Slc25a5, Q9CQQ7/Atp5f1, or P12787/Cox5a), and prion disease (e.g., down-regulated Q05144/Rac2)." (PMID 40006055, 2025).
rheumatoid arthritis (2 papers, 2024 to 2025). A chronic, systemic autoimmune disorder characterized by inflammation in the synovial membranes and articular surfaces. "Finally, we found through qRT-PCR experimental analysis that NDUFB3, NGLY1, and SLC25A4 are highly expressed in rheumatoid arthritis compared with normal tissues." (PMID 39421742, 2024). "Notably, SLC25A4 has also been reported to be upregulated in human PBMCs treated with vitamin D3, a key modulator of the immune system, and downregulated in PBMCs from patients with rheumatoid arthritis." (PMID 40649814, 2025).
Skeletal myopathy (2 papers, 2018 to 2024). "Furthermore, recessive AGK variants cause potentially fatal infantile respiratory and cardiac failure, but recessive SLC25A4 variants cause a childhood-onset intermediate form of cardiac and skeletal myopathy." (PMID 38804971, 2024). "AGK and SLC25A4 variants often cause cardiac and skeletal myopathy frequently with mtDNA depletion." (PMID 38804971, 2024). "This case expands the known phenotype of SLC25A4 disease to include childhood-onset mild skeletal myopathy without evidence of cardiac, brain, or extraocular muscle involvement." (PMID 30046662, 2018).
22q11.2 deletion syndrome (1 paper, 2021). 22q11.2 deletion syndrome (DS) is a chromosomal anomaly which causes a congenital malformation disorder whose common features include cardiac defects, palatal anomalies, facial dysmorphism, developmental delay and immune deficiency. "Recent work suggests that SLC25A1 and SLC25A4 are hub genes in the network of the perturbed brain proteome associated with 22q11.2 deletion syndrome." (PMID 34312306, 2021).
acute myeloid leukemia (1 paper, 2022). Acute myeloid leukemia (AML) is a group of neoplasms arising from precursor cells committed to the myeloid cell-line differentiation. "In contrast, the expression of SLC25A4, SLC25A8, SLC25A12, and SLC25A25 was associated with better prognosis of patients in acute myeloid leukemia." (PMID 36254139, 2022).
Allergy (1 paper, 2021). An allergy is an immune response or reaction to substances that are usually not harmful. "Pathways related to intracellular signalling pathway, stress response, VEGF and MTOR related, the latter showed in the last years to be related with allergy; and oxidative phosphorylation are up-regulated, like FOXP1, SERPIN family, SOD2, caspase family, PGF, CYB5B, SERP1 and SLC25A4." (PMID 34784380, 2021).
atherosclerosis (1 paper, 2025). A disease characterized by the build-up of fatty material and calcium deposition in the arterial wall resulting in partial or complete occlusion of the arterial lumen. "Based on these findings, we hypothesized that SLC25A4 may play a role in inducing the formation of NETs and potentially contribute to the acceleration of atherosclerosis by regulating mitophagy." (PMID 40053030, 2025).
cervical squamous cell carcinoma (1 paper, 2022). A squamous cell carcinoma arising from the cervical epithelium. "Some genes of SLC25 were associated with poor prognosis of patients in cervical squamous cell carcinoma and endocervical adenocarcinoma, including SLC25A4, SLC25A5, SLC25A8, SLC25A14, SLC25A12, SLC25A23, and SLC25A41." (PMID 36254139, 2022).
cholangiocarcinoma (1 paper, 2022). A carcinoma that arises from the intrahepatic biliary tree (intrahepatic cholangiocarcinoma) or from the junction, or adjacent to the junction, of the right and left hepatic ducts (hilar cholangiocarcinoma). "Notably, SLC25A4 had more deletion of copy number in cholangiocarcinoma, sarcoma and lung squamous cell carcinoma." (PMID 36254139, 2022). "SLC25A4 and SLC25A24 had more copy number deletion in cholangiocarcinoma, sarcoma, and lung squamous cell carcinoma." (PMID 36254139, 2022).
chronic progressive external ophthalmoplegia (1 paper, 2018). "A family of BD and chronic progressive external ophthalmoplegia (CPEO) caused by a mutation of the mitochondrial adenine nucleotide translocator 1 (ANT1, SLC25A4) implicated that ANT1 mutations confer a risk of BD." (PMID 29892051, 2018).
colon adenocarcinoma (1 paper, 2022). "For detailed results at tissue mRNA level, SLC25A4 was lowly expressed in stomach adenocarcinoma and colon adenocarcinoma." (PMID 36254139, 2022). "Expression of mRNA level showed that SLC25A4 was downregulated in stomach adenocarcinoma and colon adenocarcinoma." (PMID 36254139, 2022).
dilated cardiomyopathy (1 paper, 2025). Cardiomyopathy which is characterized by dilation and contractile dysfunction of the left and right ventricles. "Necroptosis, neutrophil extracellular trap formation, cardiac muscle contraction, and dilated cardiomyopathy, among others, are some pathways affected by downregulated proteins such as Pgam5, Slc25a4, and H2ax as well as Myl2, Myl3, Atp2a1, and Tpm2." (PMID 41011134, 2025).
head and neck squamous cell carcinoma (1 paper, 2022). A squamous cell carcinoma that arises from any of the following anatomic sites: lip and oral cavity, nasal cavity, paranasal sinuses, pharynx, larynx, and salivary glands. "In head and neck squamous cell carcinoma, SLC25A9, SLC25A23, SLC25A4, and SLC25A5 all showed decreased expression." (PMID 36254139, 2022).
leukemia (1 paper, 2021). A malignant (clonal) hematologic disorder, involving hematopoietic stem cells and characterized by the presence of primitive or atypical myeloid or lymphoid cells in the bone marrow and the blood. "In stark contrast, the expression profiles of the three main ANT isoforms were entirely distinct between PBMC and leukemia mitochondria, highlighted by reduced ANT1 (SLC25A4) and increased ANT2 (SLC25A5) and ANT3 (SLC25A6) in leukemia." (PMID 34132194, 2021).
lung adenocarcinoma (1 paper, 2022). A carcinoma that arises from the lung and is characterized by the presence of malignant glandular epithelial cells. "Therefore, signaling pathways related to bile acid metabolism may be a potential therapeutic target for invasive lung adenocarcinoma, as shown in our results for SLC25A4." (PMID 36254139, 2022).